NF2 (NF2, moesin-ezrin-radixin like (MERLIN) tumor suppressor)
Diseases named in the same sentence as NF2 in open-access papers (continued):
Sharing a sentence is not in itself a finding about the gene and the disease.
spinal meningioma (10 papers, 2018 to 2024). Spinal meningioma isa rare type of spinal cord cancer. "Predisposing genetic conditions associated with the presence of spinal meningiomas include NF2, schwannomatosis, multiple endocrine neoplasia type 1 (MEN 1), and, rarely, neurofibromatosis type 1 (NF1) and Von Hippel Lindau (VHL) syndrome." (PMID 38611105, 2024). "For example, spinal ependymomas commonly show mutations in the NF2 gene, whereas spinal meningiomas often have chromosomal irregularities, including the loss of chromosome 22." (PMID 39001422, 2024). "Neither of the study patients with MPMN had clinical or radiological evidence of intracranial or spinal meningiomas or a history of NF-2-associated syndromes." (PMID 30542514, 2018). "When anaplastic spinal meningiomas occur, they have been reported primarily either as primary lesions with concurrent NF2 diagnosis or as metastases from intracranial meningiomas undergoing “malignant transformation” via seeding of the cerebrospinal fluid." (PMID 38611105, 2024). "In spinal schwannoma, one study reported a mutation in the large tumor suppressor kinase 1 gene (LATS1), a downstream mediator of NF2, but the clinical relevance of these alterations remains unknown in spinal meningiomas." (PMID 36713513, 2022). "NF2 may show schwannoma (typically bilateral vestibular tumors) and cranial/spinal meningiomas and ependymomas." (PMID 34574050, 2021).
malignant peripheral nerve sheath tumor (9 papers, 2017 to 2024). Malignant peripheral nerve sheath tumor (MPNST) is a rare and often aggressive soft tissue sarcoma occurring in a wide range of anatomical sites. "Several additional proteases have been implicated in NF1 and malignant peripheral nerve sheath tumors (MPNSTs), two neuro-cutaneous syndromes that share features with NF2." (PMID 32848608, 2020). "The other patient, a patient with NF2, was diagnosed with multiple other tumors including a highly aggressive malignant peripheral nerve sheath tumor (MPNST), which presumably caused his death." (PMID 38265489, 2024). "The findings strongly indicate that selective RKIP inducers could hold promise for treating both NF2 syndrome and an NF2-deficient malignant peripheral nerve sheath tumor (MPNST)." (PMID 38786085, 2024).
neurocutaneous disorder (9 papers, 2009 to 2025). "NF2 is an autosomal dominantly inherited neurocutaneous disorder due to mutations in NF2 on 22q12.2." (PMID 19333415, 2009).
peritoneal mesothelioma (9 papers, 2015 to 2025). A benign or malignant mesothelial neoplasm that arises from the peritoneum. "NF2 mutations were identified in 21–35% of cases of peritoneal mesothelioma." (PMID 40725095, 2025). "Data presented in this report provide further evidence for the role of tumor suppressor genes such as CDKN2A, NF2 in the pathogenesis of peritoneal mesothelioma, and presents several other mutations that may also play key roles in the natural history of this disease." (PMID 25798586, 2015). "In our cohort, NF2 is altered in 32.8% of pleural and 26.5% of peritoneal mesothelioma, compared to other studies with alterations in about 20% of the cases." (PMID 36138075, 2022). "Furthermore, in the peritoneal mesothelioma cohort in the previously cited study, the most common alterations detected in peritoneal mesothelioma were inactivating mutations in BAP1 (47.9%), NF2 (26.5%), CDKN2A (25.9%), CDKN2B (19.5%) and PBRM1 (15.8%)." (PMID 38136262, 2023). "Similarly, a combination of CDKN2A homozygous deletion and NF2 hemizygous loss is a negative prognostic factor for patients with peritoneal mesothelioma." (PMID 37180489, 2023). "Likewise, a combination of homozygous CDKN2A deletions and hemizygous NF2 loss in peritoneal mesotheliomas has been shown to be an independent negative prognostic factor for both PFS and OS." (PMID 29565815, 2018). "The development of peritoneal mesothelioma was observed in genetically engineered mice heterozygous in Nf2 without asbestos exposure." (PMID 32083805, 2020).
prostate carcinoma (9 papers, 2018 to 2025). A carcinoma that arises from epithelial cells of the prostate gland. "The second most common cause of cancer mortality in the male US population is prostate cancer, which has associations with mutations in the NF2 gene as well." (PMID 39796693, 2024). "For example, in prostate cancer, inactivation of NF2 is associated with increased invasiveness and chemoresistance." (PMID 32337368, 2020). "A study investigating several prostate cancer cell lines revealed that NF2 expression was significantly lowered in these cells." (PMID 39796693, 2024). "Although the role of NF2 downregulation in prostate carcinoma is well-defined, the specific pathways involved in NF2 inhibition have yet to be explored and should be a focus in future studies." (PMID 39796693, 2024). "More specifically, the NF2 activity in these prostate carcinoma cell lines were suppressed by the upregulation of p-21 activating kinases (PAKs) that constitutionally phosphorylate NF2." (PMID 39796693, 2024). "Therefore, it was concluded that Merlin was inactivated in DU145 prostate cancer cells by PAK-mediated inhibition, further providing evidence for the role of NF2 in prostate cancer development." (PMID 39796693, 2024). "The upstream regulators identified in advanced-stage prostate cancer in both PC3 and DU145 cells includes (i) AGO2, (ii) SSB, and (iii) neurofibromatosis 2 (NF2), and (iv) DICER1." (PMID 31756185, 2019). "In mesotheliomas, breast cancers, and prostate cancers without genetic or transcriptional inactivation of NF2, there is evidence of functional Merlin inactivation at the post-translational modification level." (PMID 38338806, 2024). "In the present study the expression of AGO2, SSB, and NF2 is downregulated in early-stage cancer and upregulated in advance-stage cancer; whereas PPARA was overexpressed and DICER1 was inhibited across all stages of prostate cancer." (PMID 31756185, 2019). "The prostate cancer case also had P/LPGVs in BARD1, NF2, and POLE, all of which were not reported on the TGP." (PMID 41465149, 2025).
skin tumours (9 papers, 2009 to 2025). "In their 2009 review of the clinical manifestations of NF2, Asthagiri and colleagues reported that skin tumors occur in 59–68% of patients with NF2 and include skin plaques, subcutaneous and intradermal tumors." (PMID 32591014, 2020). "About 70% of NF2 patients have skin tumours (intracutaneous plaque-like lesions or more deep-seated subcutaneous nodular tumours)." (PMID 19545378, 2009). "Of around 70% of patients with NF2 who develop skin tumors, only 10% have more than 10 skin tumors." (PMID 32591014, 2020). "About 70% of NF2 patients have skin tumours, but only 10% have more than ten skin tumours." (PMID 19545378, 2009).
thyroid cancer (9 papers, 2011 to 2025). "Others demonstrated that the loss of Nf2 or Ras activation was insufficient to independently induce thyroid cancers, while the cooperation of Ras and Nf2 led to poorly differentiated thyroid carcinomas with increased MAPK signaling." (PMID 34065786, 2021). "The authors demonstrated that loss of Nf2 or Ras activation is insufficient to independently induce thyroid cancer in mice, but their combination was highly tumorigenic." (PMID 34065786, 2021). "As far as we know, NF2 is the only commonly mutated driver gene in the Hippo pathway in thyroid cancer." (PMID 34065786, 2021). "We identified NF2 mutations associated with resistance to the BRAF inhibitor dabrafenib in BRAF mutant thyroid carcinoma cell lines." (PMID 33205120, 2020). "Notably, in thyroid cancer, low NF2 expression is closely associated with tumor aggressiveness and poor prognosis in patients." (PMID 39712860, 2025). "Interestingly, studies on thyroid cancer in mice and human cells alike have shown Hippo signaling pathway involvement in NF2-mutated tumors through the Ras pathway." (PMID 39796693, 2024). "The specific biological pathway involved in human NF2-mutant thyroid cancers is a subject for further study, but current evidence provides support for Hippo signaling and Ras signaling involvement." (PMID 39796693, 2024). "We speculate that SMARCB1 is an important effector in addition to NF2 and CHEK2 inactivation among thyroid cancers with chromosome 22q loss." (PMID 32380731, 2020). "In the current study, our results showed that MAPK8IP1P2 activated Hippo signaling by sponging miR-146b-3p to disrupt targeting effect of miR-146b-3p on NF2, RASSF1, and RASSF5, which inhibited anoikis resistance and lymphatic metastasis of thyroid cancer." (PMID 33489905, 2020). "Mechanistically, MAPK8IP1P2 activated Hippo signaling by sponging miR-146b-3p to disrupt the inhibitory effect of miR-146b-3p on NF2, RASSF1, and RASSF5 expression, which further inhibited anoikis resistance and lymphatic metastasis in thyroid cancer." (PMID 33489905, 2020). "Overexpression of miR-146b-3p directly targeted NF2, RASSF1, and RASSF5 in thyroid cancer cells and inactivated Hippo signaling, which further promoted anoikis resistance and lymphatic metastasis of thyroid cancer." (PMID 33489905, 2020). "Collectively, our findings clarify that MAPK8IP1P2 activates Hippo signaling by sponging miR-146b-3p to disrupt the inhibitory effect of miR-146b-3p on NF2, RASSF1, and RASSF5 expression in thyroid cancer." (PMID 33489905, 2020). "Review articles discussing these models have been published, including examples of Hras or Kras knock-in mice crossed with cooperating genetic alterations commonly found in advanced thyroid cancers driven by oncogene RAS (e.g., NF2, EIF1AX and PI3K pathway genes)." (PMID 39874138, 2025). "Mechanistic investigations revealed that MAPK8IP1P2 activated Hippo signaling by sponging miR-146b-3p to disrupt the inhibitory effect of miR-146b-3p on NF2, RASSF1, and RASSF5 expression, which further inhibited anoikis resistance and lymphatic metastasis in thyroid cancer." (PMID 33489905, 2020). "In summary, our results demonstrate that MAPK8IP1P2 activates Hippo signaling by sponging miR-146b-3p as a ceRNA to disrupt the inhibitory effect of miR-146b-3p on NF2, RASSF1, and RASSF5 expression, which further suppresses lymphatic metastasis of thyroid cancer." (PMID 33489905, 2020). "Importantly, miR-146b-3p mimics not only reversed the NF2, RASSF1, and RASSF5 level enhanced by MAPK8IP1P2 overexpression, but also inactivated Hippo signaling in MAPK8IP1P2-overexpressing thyroid cancer cells as indicated by elevated the luciferase reporter activity of HOP-Flash." (PMID 33489905, 2020).
colorectal cancer (8 papers, 2017 to 2025). A primary or metastatic malignant neoplasm that affects the colon or rectum. "CDH1 is associated with colorectal cancer through its involvement in the E-cadherin-NF2-Hippo-YAP signaling pathway." (PMID 38536014, 2024). "Here we find that a top co-associated receptor, Neogenin (NEO1), inhibits colorectal cancer (CRC) and Glioma in situ growth and metastasis by forming a complex with Merlin (NF2), and subsequent simultaneous promoting the phosphorylation of YAP." (PMID 36746934, 2023). "Of note, we recently demonstrated that PrPC levels positively control the phosphorylation of NF2 on serine 518, itself negatively regulating NF2 activity, in colorectal cancer." (PMID 34638517, 2021). "However, this sample was also positive for another frameshift mutation in NF2 c.1702_1703delAG (p.Arg568fs), which would not have been uncovered by a panel focused solely on genes predisposing for colorectal cancer and gastrointestinal malignancies." (PMID 28526081, 2017). "Furthermore, significant variations in expression profiles and functional characteristics of key components (including VGLL4, NF2, and RASSF family members) have been documented across various malignancies (e.g., breast, hepatic, and colorectal cancers)." (PMID 40486910, 2025).
hearing loss (8 papers, 2012 to 2026). "Uncertainty remains in the identification of primary therapeutic targets for treatment of hearing loss in NF2-SWN." (PMID 40895102, 2025). "Recent evidence implicates neuroimmune interactions and inflammation within the cochlear microenvironment as potential contributors to hearing loss in NF2-SWN." (PMID 40895102, 2025). "Both NF2 and VS are often associated with hearing impairments, primarily due to damage to the auditory nerve." (PMID 39438593, 2024). "Symptoms included hearing loss (n = 7; median age 12 ± 3.4 years), which led to an NF2 diagnosis in three cases, peripheral facial paralysis (n = 5; median age 9 ± 3.9 years [range 6–15]) or vestibular damage (n = 3; median age 11 ± 4.5 years [range 6–15])." (PMID 35729665, 2022). "There is growing interest in developing technologies to identify molecular biomarkers of hearing loss in sporadic and NF2-associated VS." (PMID 33604573, 2021). "The mechanism by which hearing loss occurs in sporadic and NF2-associated VS has been intensely studied yet still remains incompletely understood." (PMID 33604573, 2021). "Here, we examined radiographic and audiometric findings associated with hearing loss in NF2 to better understand the pathophysiologic mechanisms underlying onset and progression of hearing loss in this hereditary neoplastic disorder." (PMID 23049959, 2012). "To identify markers for hearing loss and underlying pathophysiological mechanisms, we prospectively analyzed the clinical, imaging, and audiologic findings in a large cohort of NF2 patients." (PMID 23049959, 2012). "The most common imaging findings identified in CVS-associated hearing loss in NF2 was the presence of elevated intralabyrinthine perilymphatic protein and the presence of cochlear aperture obstruction on MR-imaging." (PMID 23049959, 2012). "Here, we asked whether FLAIR hyper-intensity could serve as a predictive biomarker for hearing loss in NF2 patients with VS." (PMID 41586863, 2026). "For instance, hearing loss in NF2 has an unpredictable onset and variable progression, which may be gradual, stepwise, relapsing and remitting, or sudden and complete." (PMID 23049959, 2012). "Because hearing loss in NF2 may be caused by end organ degeneration (cochlea) from accumulated protein, the functional consequences of tumor location as it relates to the cochlear aperture appears to play an important role in the pathogenesis of hearing loss." (PMID 23049959, 2012). "FOXI1, NF2, MYO15A and CLIC5 genes, were among others associated with swimming impairment and hearing loss." (PMID 34829759, 2021). "In Case 2, a 54-year-old female patient and her two sisters were diagnosed with NF2-SWN, while their mother exhibited hearing loss symptoms but lacked definitive imaging findings, thus being classified as a suspected NF2-SWN case." (PMID 41209567, 2025). "While equivalent clinical data do not yet exist for treating NF2 and hearing loss, several preclinical animal studies have shown promising results." (PMID 33604573, 2021).
intrahepatic cholangiocarcinoma (8 papers, 2021 to 2025). A carcinoma that arises from the intrahepatic bile duct epithelium in any site of the intrahepatic biliary tree. "1-mo-old Nf2 single-mutant livers (Alb-Cre;Nf2flox/flox) developed focal intrahepatic cholangiocarcinoma (ICC) at the surface of the liver." (PMID 36522128, 2022). "Another study has revealed that WWC1 cooperated with NF2 to mitigate the malignant progression of intrahepatic cholangiocarcinoma by activation of LATS1/2 and inhibition of YAP/TAZ activity." (PMID 36158126, 2022). "For example, Nf2 conditional null mice show hyperproliferation of hepatic progenitor cells, known as a ductular reaction, and develop both HCC and intrahepatic cholangiocarcinoma (ICC)." (PMID 33808155, 2021).
sarcoma (8 papers, 2019 to 2025). A usually aggressive malignant neoplasm of the soft tissue or bone. "No cancer-associated alterations could be detected in teratoma derived from mRNA-derived hiPSCs and only two genes (FUS, NF2) were found altered in Sendai-derived teratoma that were associated with human sarcoma." (PMID 31105870, 2019). "It was found that sarcomas O-P2, L-P5, and Rm-P6 carry mutations in the CTNNB1 (gene accession number: NG_013302.2), KIT (gene accession number: NG_007456.1), and NF2 (gene accession number: NG_009057.1) genes." (PMID 41300532, 2025). "Accordingly, sarcoma incidence increases in hereditary neurofibromatosis patients with carrying deletions of the RAS negative regulator genes NF1 or NF2." (PMID 34294128, 2021). "Interestingly, NF2 mutations might contribute to the maintenance of rare aggressive sarcomas." (PMID 34294128, 2021).
skull base meningioma (8 papers, 2019 to 2025). A meningioma that arises from the skull base. "In this study, we successfully created a Cas9 mouse model of skull base meningioma initiated with a genetic defect in Nf2 and the combined loss of P15Ink4b, P16Ink4a, and P19Arf." (PMID 39996452, 2025). "In our study, with some modifications to the Cre‐lox system, we created a new mouse model of skull base meningioma using Nf2 gene inactivation and the combined loss of P15Ink4b, P16Ink4a, and P19Arf." (PMID 39996452, 2025). "TRAF7 mutations are found to be enriched in anterior skull base meningiomas, which are mesodermal in origin and tend to have non-NF2 genomic patterns." (PMID 40867323, 2025). "Our study confirmed that NF2 mutations define a distinct subclass of non-skull base meningiomas that have a predilection to progress in grade." (PMID 36882706, 2023). "In this study, we developed a novel mouse model of skull base meningioma based on Nf2 gene inactivation." (PMID 39996452, 2025). "In cases of NF2-mutant skull base meningiomas refractory to surgery and radiation, currently, there is no effective chemotherapy; however, PIK3CA, SMO and AKT1 represent promising future therapeutic targets." (PMID 40075786, 2025). "Concerning the three NF2-wild type IVMs, none had mutations in AKT1, PIK3CA or SMO genes, which are typically altered in skull base meningiomas." (PMID 35049691, 2022).
cataract (7 papers, 2011 to 2025). Partial or complete opacity of the crystalline lens of one or both eyes that decreases visual acuity and eventually results in blindness. "The biological basis for NF2-associated cataracts and subcapsular opacities is poorly understood, though they presumably result from loss of merlin and dysfunction of intracellular signaling in these cellular populations, though this requires further analysis." (PMID 31161239, 2020). "NF2 is known to be associated with several ocular manifestations, including subcapsular lenticular opacities (cataracts) and ophthalmic hamartomas." (PMID 30356733, 2018). "Moreover, a lens-specific loss of Nf2 resulted in subcapsular cataracts, in which the lens fiber cells retained their progenitor status within a poorly differentiated lens." (PMID 33233821, 2020). "Previous studies have indicated that more than 40–70% of children with NF2 have cataracts, retinopathy, or both." (PMID 40852360, 2025). "A reduction of YAP expression in Nf2 mutant lenses ameliorated the cataracts and the disorganised lens phenotype." (PMID 33233821, 2020). "Juvenile cortical wedge cataracts may be observed shortly after birth in patients with NF2, with posterior subcapsular opacities developing later in life." (PMID 31161239, 2020). "In a series of 15 other NF2 patients, 12 patients had an epiretinal membrane in the macular or paramacular area and 11 patients had central posterior cortical, subcapsular, or peripheral cortical lens opacities." (PMID 21850187, 2011).